ENSG00000267127 (novel protein)
Gene: Protein-coding gene on chromosome 18 (80,034,346 to 80,097,088, forward strand). Ensembl gene ENSG00000267127.
Genetic constraint (gnomAD): Missense variants: 95 observed, 72.94 expected, observed/expected ratio (o/e) 1.3, 90% interval 1.1 to 1.54. Synonymous variants: 35 observed, 33.04 expected, observed/expected ratio (o/e) 1.06, 90% interval 0.81 to 1.4.